ERBB2 (erb-b2 receptor tyrosine kinase 2)
Diseases named in the same sentence as ERBB2 in open-access papers (continued):
Sharing a sentence is not in itself a finding about the gene and the disease.
breast cancer (continued). "Similarly, YWHAZ overexpression was significantly associated with reduced disease-free survival/overall survival and earlier time to disease recurrence, and death in breast cancer by combining with elevated levels of Akt, FOXM1, ErbB2, LOC441453 and LAPTM4B 31, 32, 35, 36, 39, 78-80." (PMID 32127952, 2020). "However, no increase in NDRG1 expression was evident in ErbB2 breast cancer cells cultured in the presence of MEDICA." (PMID 32695336, 2020). "Triple-negative breast cancer (TNBC) accounts for 15–20% of all breast cancer cases and is a subtype of breast cancer characterized by the lack of oestrogen receptor (ER), progesterone receptor (PR) and ErbB-2/human epidermal growth factor receptor 2 (HER-2) expression." (PMID 32661222, 2020). "In the phase III PALOMA-3 study, patients with advanced-stage, hormone receptor positive, ErbB2-negative breast cancer that had progressed after endocrine therapy were assigned for treatment with either the endocrine therapeutic agent fulvestrant alone or in combination with palbociclib." (PMID 33255177, 2020). "Together with the low concordance between the copy numbers and gene expression levels of ERBB2 in CMT (r = 0.09, measured in this cohort), unlike in human breast cancers (r = 0.857), we can assume a reduced role and limited clinical value for ERBB2 in CMT, as was previously proposed." (PMID 32680987, 2020). "By further considering ERBB2 status and smaller age groups, we found differing trends in hormone receptor–positive and hormone receptor–negative breast cancers based on positive ERBB2 expression, enabling us to identify additional racial/ethnic and age group variation in trends." (PMID 32804214, 2020). "ErbB2-positive subtype, together with the hormone receptor-positive/ErbB2-negative and triple-negative subtypes, represents the major molecular classification of breast cancer patients that guides the selection of therapeutic strategies in the clinical treatment." (PMID 32327714, 2020). "Furthermore, activating mutations in ERBB2, which encodes HER2, and ESR mutations in the ligand binding domain were identified in non-responding breast cancer patients treated with anti-HER2 antibodies and hormone therapy." (PMID 32099048, 2020). "Thus, neither morphology nor the size distribution of EVs emitted by ErbB2-positive breast cancer cells seems to be affected by trastuzumab or by the sensitivity of the cells to this drug." (PMID 33023655, 2020). "While the majority of breast cancers are sensitive to the endocrine therapy, patients with triple-negative breast cancer (TNBC) exhibit poor outcomes as the subtype lacks effective therapeutic targets including ER, PR and human epidermal growth factor receptor 2 (HER2)/ErbB2." (PMID 32106418, 2020). "Taken together, this suggests that ERBB2 requires EGFR or other members of the family possibly to dimerize for activation, such that down‐regulation of EGFR and potentially other members suppress the functionality of ERBB2, as has been previously reported in breast cancer." (PMID 30304546, 2019). "In addition, Notch3 pivotal role in the proliferation of ErbB2-negative breast cancer cell lines has been demonstrated." (PMID 31379945, 2019). "ERBB2 is a key regulator in breast cancer, and the strong negative feedback association between GATA4 and ERBB2 may contribute to the transcriptional dysregulation of ERBB2 gene expression in breast cancer." (PMID 30872657, 2019). "Breast cancer is a heterogeneous disease with several subtypes, defined based on the presence or absence of estrogen receptors (ERs), progesterone receptors (PRs), and epidermal growth factor receptor-2, the receptor tyrosine-protein kinase erbB-2 (ERBB2/Her2)." (PMID 31195298, 2019).
breast cancer (continued). "(c-d) Scatter plots of ITGA3 and ERBB2 expression of breast cancer cell lines, classified as luminal-, basal-, and post-EMT-like show clustering of luminal-like cell lines to low ITGA3 expression: (c) HER2+ and triple-negative-enriched breast cancer panel (n = 30)." (PMID 31101121, 2019). "However, there were also breast cancer cell lines which showed high lapatinib cytotoxic effect (MDA-MB-175: 0.012 μM, EFM-19: 4.6 μM, MCF-7: 7.7 μM and MDA-MB-435: 8.5 μM) but expressed a moderate or low level of both ErbB1 and ErbB2 (2.2 to 20 ng/mg)." (PMID 31905843, 2019). "Notably, ERBB2 signaling, which is essential for trabeculation, induces EMT in breast cancer cells." (PMID 31868165, 2019). "Transgenic mice overexpressing epidermal growth factor receptor 2 (ErbB2) under the transcriptional control of the mouse mammary tumor virus (MMTV) promoter represent a spontaneous mammary tumor model, which does not require any hormonal exposure for tumorigenesis." (PMID 30621730, 2019). "Human epidermal growth factor receptor 2 (HER2/ERBB2) is overexpressed in approximately 25% of breast cancers and drives hyperactivation of the HER2 pathway via downstream signaling initiated by receptor homo- or hetero-dimerization with other HER family members (HER2/HER2, HER2/EGFR, HER2/HER3)." (PMID 31796073, 2019). "Breast cancer can be divided into subtypes according to histopathological features such as progesterone receptor (PR), estrogen receptor (ER), or erb-b2 receptor tyrosine kinase 2 (ERBB2 or HER2) status, and include ER-positive, HER2-positive, or triple-negative breast cancer." (PMID 30326937, 2018). "Moreover, miR-125b is part of a 10-miR classifier which significantly predicts 5-year distant relapse free survival in endocrine treated, hormone receptor positive and ERBB2 negative breast cancer patients." (PMID 29507672, 2018). "Moreover, ErbB2 overexpression has been positively correlated with lymph node metastasis in breast cancers." (PMID 30241301, 2018). "TNBC and ERBB2 negative breast cancer leads to brain metastasis in ~20–50% of cases." (PMID 30697531, 2018). "Thus, TFEB is most likely not involved in the regulation of the ErbB2-induced, invasion-promoting lysosomal alterations in breast cancer cells, since ErbB2 activation leads to the activation of the mTOR and MAPK-ERK signaling pathways." (PMID 29396433, 2018). "TN breast cancers are aggressive with poor patient prognosis and because they lack expression of the ER and the progesterone receptor (PR) and do not have amplification of ERBB2, they do not respond to current targeted therapies." (PMID 29339815, 2018). "However, seen the exclusive high expression of ERBB2 in the luminal subtype, outcome may rather be compared to HER2+ breast cancer, shown to present a significant inferior outcome compared to the basal subtype." (PMID 29899832, 2018). "The prognostic signatures evaluated provided significant information to help determine appropriate candidates consisting of patients with ER-positive, ERBB2-negative breast cancer, for whom chemotherapy and extended endocrine therapy might not be indicated." (PMID 29450494, 2018). "The levels of AHR, AHR nuclear translocator (ARNT) and AHR repressor (AHRR) mRNA expression were analyzed in a cohort of 439 breast tumors, demonstrating a weak association between high AHR expression and age greater than fifty years and ERα-negative status, and HR-/ERBB2 breast cancer subtypes." (PMID 29320557, 2018). "Efficacious therapies of breast cancers resistant to ErbB2 antagonists are not available." (PMID 30545388, 2018). "This can most likely be explained by the fact that none of the Wilkerson subtypes have (yet) been associated with a driver event, unlike breast cancer where ESR1 and ERBB2 have been identified as strong drivers giving rise to specific subtypes of breast cancer." (PMID 30379847, 2018).
breast cancer (continued). "Since ganetespib-mediated effects on apoptosis in ErbB2+ breast cancer cells have not been well-documented, we treated BT474 and SKBR3 cells with ganetespib (0-250 nM) for 16 hours, followed by Annexin V and propidium iodide (PI) staining to examine the effects of ganetespib on apoptosis." (PMID 29717218, 2018). "Accurate determination of the predictive markers human epidermal growth factor receptor 2 (HER2/ERBB2), estrogen receptor (ER/ESR1), progesterone receptor (PgR/PGR), and marker of proliferation Ki67 (MKI67) is indispensable for therapeutic decision making in early breast cancer." (PMID 28490348, 2017). "Hence, ErbB2 ubiquitination and subsequent proteasomal degradation does not seem to be involved in the effect of selumetinib on ErbB2 in detached breast cancer cells." (PMID 29285258, 2017). "Given that Mek inhibition downregulates ErbB2 protein in detached breast cancer cells without downregulating the ErbB2 mRNA, we tested whether Mek inactivation blocks ErbB2 protein stability in these cells." (PMID 29285258, 2017). "Epidermal growth factor (EGF) is a crucial factor in mammary gland development and EGFR-targeted therapy provides some promising effects in patients with triple-negative (estrogen receptor-, progesterone receptor-, and erb-b2 receptor tyrosine kinase 2-negative) breast cancer." (PMID 29212252, 2017). "However, how EGR2 contributes to breast cancer however is not clear, its expression has been suggested to drive both the expression of both Erbb2, as well as aromatase expression." (PMID 28687085, 2017). "Furthermore, Manzano and colleagues reported that PLPP4 was upregulated in only the estrogen receptor (ER)-ERBB2+ subgroup, but not in other subtypes of breast cancer, suggesting a specific role of PLPP4 in ER-ERBB2+ subtypes." (PMID 28851360, 2017). "It is known that ErbB2 levels are not constant in many ErbB2-positive breast cancers." (PMID 29285258, 2017). "In addition to the ERBB2-positive subtype of breast cancer (ER and PR negative), the luminal B subtype is also ERBB2 positive, but this subtype is ER and PR positive and has different clinical characteristics and prognosis." (PMID 28415602, 2017). "The suppression of ERBB2 by siRNA in tamoxifen-resistant breast cancer cells resulted in a decrease in the proliferative ability of the cells, which reconfirms the involvement of the ERBB2/ERBB3 pathways in the development of chemoresistance to breast cancer cells." (PMID 29299178, 2017). "Thus, Mek-dependent ErbB2 expression in detached breast cancer cells is critical for their ability to grow without adhesion to the ECM and for their trastuzumab sensitivity." (PMID 29285258, 2017). "Similarly, some other eRGs such as FOXA1 and ERBB2, were also found to be differentially expressed in basal vs. non-basal breast cancer samples probably owing to the differential enhancer methylation." (PMID 28621677, 2017). "Moreover, the Mek inhibitor upregulated, rather than downregulated, the ErbB2 mRNA in detached human breast cancer cells HCC-1419." (PMID 29285258, 2017). "One model that we used to study the role of Mek in the ability of ErbB2-expressing breast cancer cells to grow without adhesion to the ECM represents MCF-ErbB2 cells derived from non-malignant breast epithelial cells MCF10A by infection with a wild type ErbB2-encoding retrovirus." (PMID 29285258, 2017). "In addition, ERRF is transcriptionally regulated by the E2-ER signaling pathway in ER/PR-positive but ERBB2-negative breast cancer cells." (PMID 28415602, 2017). "Indeed, for example in ERBB2-amplifying breast cancers, there are many genes within the ERBB2 amplicon that are not co-expressed, despite high copy number co-amplification, with ERBB2 CNV." (PMID 29069713, 2017). "Finally, we checked whether this TOM1L1 invasive role was conserved in breast tumour cells by overexpressing TOM1L1 in the ERBB2- and TOM1L1-negative breast cancer cell line MDA-MB-231." (PMID 26899482, 2016).
breast cancer (continued). "Moreover, adjuvant or neoadjuvant treatment of ErbB2-positive breast cancer with lapatinib and ErbB2-specific trastuzumab does not significantly improve disease-free survival, compared to trastuzumab alone." (PMID 27286447, 2016). "Taken together, our data indicates little to no role for IRSs in ErbB2 action in breast cancer." (PMID 27765041, 2016). "However, clinical data show that about 70% of the patients with ErbB2-overexpressing breast cancer do not respond to trastuzumab treatment." (PMID 27564098, 2016). "Copy number aberrations (CNAs) in known breast cancer driver genes present in the PDTXs included gains/amplifications of MYC (78%), CCNE1 (34%), ZNF703 (25%), CCND1 (31%), MDM2 (25%), and ERBB2 (9%) and deletions of PTEN (41%), PPP2R2A (72%), CDKN2A (47%), and CDKN2B (47%)." (PMID 27641504, 2016). "These and similar results in the AR-positive, ER-positive, ErbB2 active cell line, BT474, suggest that suppression of androgen signalling results in increased DNA damage and/or decreased repair in breast cancer cells that express AR, independent of ER and ErbB2 activity." (PMID 27109210, 2016). "If indeed there are different subsets of feline mammary tumors displaying opposite ERBB2 expression profiles, in parallel to what seems to happen in human breast cancer, then and once again, cat affirms itself as an extremely valuable model for either erbB-2 negative or positive human breast cancer." (PMID 29056725, 2016). "The estrogen receptor-negative and HER2+SKBR3 cell line is representative of a recently identified breast cancer subtype characterized by co-amplification of the genes coding for the HER2 membrane receptor (ERBB2) and the RARα nuclear retinoid receptor (RARA), respectively." (PMID 25961594, 2015). "Triple-negative breast cancer (TNBC), accounting for 10%–20% of breast cancer, is characterized by the lack of estrogen receptor (ER), and progesterone receptor (PgR), and low expression of the receptor tyrosine kinase ErbB2 (also known as HER2/neu)." (PMID 25883211, 2015). "Based on the differential expression of various genes, breast cancer has been categorised into five major distinct molecular subtypes with prognostic significance: luminal A; luminal B; overexpression of HER2; also known as ErbB2; breast-like; and basal-like/triple negative." (PMID 25866793, 2015). "However, in human breast cancer tissues overexpressing ErbB2, β-catenin is mainly localized in the cytoplasm rather than in the nucleus." (PMID 26268703, 2015). "Moreover, non-malignant HFF cells that express wild-type EGFR were less sensitive to the apoptotic effects of PUVA, consistent with the notion that EGFR is not responsible for induction of apoptosis in PUVA-treated ErbB2+ breast cancer cells." (PMID 24551203, 2014). "Nonetheless, the precise mechanism by which erbB3 signaling specifically upregulates Survivin, but not the functionally related molecules Mcl-1 and Bcl-xL in erbB2+ breast cancer cells remains unknown." (PMID 24886126, 2014). "In contrast, PUVA therapy using identical treatment conditions (2.5 and 5 μM 8MOP) had relatively less effect on the growth and viability of MCF7 cells, a ErbB2 non-overexpressing human breast cancer cell line and a non-malignant human foreskin fibroblast cell line (HFF)." (PMID 24551203, 2014). "However, in that study, there were only 2 ErbB2 positive breast cancer samples, which did not permit strong conclusions." (PMID 25238247, 2014). "The first study to use this approach involved applying SNS to study the evolution of aneuploidy in patients with triple-negative (ER-/PR-/HER2-) breast cancers (TNBCs; negative for, respectively, the estrogen receptor, progesterone receptor and the receptor tyrosine-protein kinase erbB-2 (HER2))." (PMID 25222669, 2014).
breast cancer (continued). "In addition, we have found that hMP-RM-1, a humanized version of the anti-erbB3 Ab MP-RM-1, exhibited similar in vitro activity to specifically downregulate Survivin in erbB2-overexpressing breast cancer cells (data not shown)." (PMID 24168763, 2013). "Up to 30% of human breast cancers are driven by overactive ERBB2 signaling and it is not clear whether AR expression affects any steps of tumor progression in this cohort of patients." (PMID 23593223, 2013). "Moreover, we explored possible correlations with clinical variables and we found a down-regulation of miR-125b in metastatic breast cancers and a significant positive correlation between EPOR and ERBB2/HER2 levels, that are both targets of miR-125b and function as competing endogenous RNAs (ceRNAs)." (PMID 24165569, 2013). "Therapies that target multiple metabolic products in combination with aberrant signaling pathways, such LKB1-AMPK-mTORC1 and ErbB2-AKT-mTORC2 may be a consideration for the future of targeted cancer treatments, particularly for HER2 resistant trastuzumab-refractory breast cancer." (PMID 23451056, 2013). "In breast cancer, MM-121’s therapeutic potential is being tested in patients with ER and/or PR positive and erbB2 negative breast cancers in combination with the aromatase inhibitor exemestane, and in patients with triple negative or erbB2 negative breast cancers in combination with paclitaxel." (PMID 24215614, 2013). "To confirm the regulation of ERBB2 by miR-125b we examined the miRNA levels in breast cancers strongly positive (positive cells > 50%) intermediately positive (positive cells = 20-50%) and weakly positive or negative (positive cells < 20%) for ERBB2." (PMID 24165569, 2013). "We previously reported that the three RTKs, erbB2, erbB3, and IGF-1R interacted with each other to form a heterotrimeric complex, which activates the downstream signaling, such as PI-3 K/Akt or MEK/MAPK pathways and Src kinase in trastuzumab-resistant breast cancer cells." (PMID 24168763, 2013). "Moreover, according to classification using the intrinsic gene expressions, the luminal-group included nine ERBB2-overexpressing breast cancer cell lines, which did not cluster as a separate group." (PMID 23601657, 2013). "These are generally defined as: basal-like breast cancer, which generally corresponds to estrogen receptor (ER) negative, progesterone receptor (PR) and HER-2 negative (i.e., triple negative), luminal A (ER positive, low grade), luminal B (ER positive, high grade) and HER-2 (or ErbB2) positive." (PMID 23839094, 2013). "In murine fibroblasts, C3H10T1/2, and human breast cancer cells, MDA-MB-361, where high levels of expression of erbB2 (naturally overexpressed) and erbB3 (ectopically or naturally overexpressed) are evident, mutual interaction between erbB2 and erbB3 takes place." (PMID 23702846, 2013). "Interestingly, previous studies on sensitivity of the panel of breast cancer cell lines to mTOR inhibitor, CCI-779, revealed that cells sensitive to CCI-779 were estrogen receptor positive, overexpressed ErbB2 and/or had lost the tumor suppressor gene product PTEN." (PMID 23389114, 2013). "Interestingly, we found that p27Kip1 levels were not reduced, and were in fact slightly higher in mammary tumors initiated by erbB2, PyMT and MNU." (PMID 24563807, 2013). "Furthermore, a significant difference (P = 0.004) was observed between serum CK level and ERBB2+breast cancer not other molecular subtypes." (PMID 23614022, 2013). "A retrospective study on a previously published breast cancer patient dataset was carried out by using Disease Specific Genomic Analysis (DSGA) to investigate the correlation of LOXL2 mRNA expression level with metastasis and survival of ErbB2-positive breast cancer patients." (PMID 23971878, 2013).